RPAP2 (RNA polymerase II associated protein 2)
Description:
Protein phosphatase that displays CTD phosphatase activity and regulates transcription of snRNA genes. Recognizes and binds phosphorylated 'Ser-7' of the C-terminal heptapeptide repeat domain (CTD) of the largest RNA polymerase II subunit POLR2A, and mediates dephosphorylation of 'Ser-5' of the CTD, thereby promoting transcription of snRNA genes. Downstream of EIF2AK3/PERK, dephosphorylates ERN1, a sensor for the endoplasmic reticulum unfolded protein response (UPR), to abort failed ER-stress adaptation and trigger apoptosis.
Synonyms: C1orf82; FLJ13150; Rtr1
Tractability: PROTAC: ubiquitination databases record sites on it.
Gene: Protein-coding gene on chromosome 1 (92,299,028 to 92,402,056, forward strand). Ensembl gene ENSG00000122484.
Subcellular location: Cytoplasm; Nucleus
Subcellular location (Human Protein Atlas): Cytosol; Nucleoli; Primary cilium
Pathways (Reactome):
Gene expression (Transcription): RNA polymerase II transcribes snRNA genes
Gene Ontology:
Molecular function: protein binding; protein serine/threonine phosphatase activity; RNA polymerase II CTD heptapeptide repeat phosphatase activity; RNA polymerase core enzyme binding
Biological process: PERK-mediated unfolded protein response; snRNA transcription; regulation of transcription by RNA polymerase II
Cellular component: cytoplasm; cytosol; nucleolus; nucleus; transcription preinitiation complex; nucleoplasm
Genetic constraint (gnomAD): Loss-of-function variants: 25 observed, 28.82 expected, observed/expected ratio (o/e) 0.87, 90% interval 0.63 to 1.21. The upper end of that interval is the gene's LOEUF score, 1.21, which puts it in group 5 of 6, group 1 being the genes least tolerant of losing a copy. Missense variants: 334 observed, 441.89 expected, observed/expected ratio (o/e) 0.76, 90% interval 0.69 to 0.83. Synonymous variants: 136 observed, 157.93 expected, observed/expected ratio (o/e) 0.86, 90% interval 0.75 to 0.99.
Homologues: Orthologues: chimpanzee RPAP2 (99% identical), macaque RPAP2 (97% identical), rabbit RPAP2 (84% identical), dog RPAP2 (83% identical), pig RPAP2 (79% identical), guinea pig RPAP2 (72% identical), mouse Rpap2 (70% identical), rat Rpap2 (70% identical), tropical clawed frog rpap2 (43% identical), zebrafish rpap2 (36% identical), Caenorhabditis elegans rpap-2 (15% identical), Drosophila melanogaster CG34183 (11% identical).
Diseases named in the same sentence as RPAP2 in open-access papers:
RPAP2 is named in the same sentence as 10 diseases in open-access papers, as found by Europe PMC text mining. Sharing a sentence is not in itself a finding about the gene and the disease. The quoted sentences say what the papers report.
breast carcinoma (2 papers, 2022 to 2025). "Circular RNA RPAP2 was found to be downregulated in breast cancer samples and cell lines and correlated with the metastasis and TNM stage of breast cancer." (PMID 40176901, 2025). "CircRPAP2, a circRNA derived from the host gene RPAP2, is expressed in breast cancer tissues and inhibits the proliferation and migration of breast cancer by competing with the association between the splicing factors SRSF1 and PTK2 pre-mRNA to modify the alternative splicing pattern of PTK2 mRNA." (PMID 35884948, 2022).
gastric cancer (1 paper, 2021). A primary or metastatic malignant neoplasm involving the stomach. "In gastric cancer cell lines (HGC-27 and MKN-45), NME2 functions as a master suppressor for apoptosis of gastric cancer by interacting with RNA polymerase II and RNA polymerase II-associated protein 2 (RPAP2)." (PMID 34628473, 2021).
hamartoma (1 paper, 2025). A benign and excessive tumor-like growth of mature cells and normal tissues which grow in a disorganized pattern. "Previous studies showed that the deletion of Fbxw7 in the liver leads to abnormal proliferation of the biliary system and the development of hamartomas, we wondered whether RPAP2 plays a causal role in this process." (PMID 39932049, 2025).
Hepatic cysts (1 paper, 2025). "This suggests that RPAP2 is a promising therapeutic target for HCC and hepatic cysts." (PMID 39932049, 2025).
hepatocellular carcinoma (1 paper, 2025). A malignant tumor that arises from hepatocytes. "The study shows that RPAP2, acting as an oncoprotein, promotes hepatocellular carcinoma (HCC) progression, with its stability being negatively regulated by FBXW7, yet positively by HSP90 and USP7." (PMID 39932049, 2025). "However, little is known about whether and how RPAP2 regulates hepatocellular carcinoma (HCC) cell growth, and how the RPAP2 stability is precisely maintained." (PMID 39932049, 2025).
cancer (1 paper, 2025). A tumor composed of atypical neoplastic, often pleomorphic cells that invade other tissues. "To investigate the role of RPAP2 in tumorigenesis, we first analyzed the correlation between RPAP2 expression and patient survival across 32 tumor types using The Cancer Genome Atlas (TCGA) database and examined its expression levels in normal tissues and primary tumors." (PMID 39932049, 2025). "Thus, future studies should define the roles of RPAP2 in the tumorigenesis of specific cancer types, either as an oncoprotein or as a tumor suppressor, using Rpap2fl/fl conditional knockout mouse model generated in this study in combination with oncogene activation or tumor suppressor inactivation." (PMID 39932049, 2025). "In response to HSP90 inhibition, the co‐chaperone CDC37 dissociates from RPAP2 and promotes the rapid degradation of RPAP2 via CRL5FBXW7, thereby enhancing the sensitivity of cancer cells to HSP90 inhibitors." (PMID 39932049, 2025).
tumor (1 paper, 2025). "Given that FBXW7 is a negative regulator of tumor growth and RPAP2, a novel FBXW7 substrate, is required for the growth and survival of HCC cells, we investigated whether RPAP2 accumulation plays a causal role in the tumor growth induced by FBXW7 knockdown." (PMID 39932049, 2025). "Furthermore, we used a xenograft tumor model to determine the causal role of RPAP2 accumulation in FBXW7 knockdown‐mediated tumor growth in vivo." (PMID 39932049, 2025). "Similarly, RPAP2 depletion completely reversed the tumor growth promotion by FBXW7 knockdown, as evidenced by the decreased tumor volume and weight." (PMID 39932049, 2025). "Collectively, these results indicate that RPAP2 expression is up‐regulated in HCC and that high RPAP2 expression is associated with advanced tumor grade and poor patient survival in HCC, implying a potential role for RPAP2 in promoting HCC development and progression." (PMID 39932049, 2025). "Additionally, RPAP2 mRNA levels were significantly elevated in HCC tissues compared to normal liver tissues, and higher RPAP2 expression was positively correlated with advanced tumor grade." (PMID 39932049, 2025). "Consistently, IHC staining of xenograft tumor tissues revealed that the knockdown of RPAP2 rescued the growth‐promoting effect of FBXW7 deprivation, as reflected by decreased staining of Ki67, a marker of cell proliferation, and increased staining of Cleaved‐Caspase‐3, a marker of apoptosis." (PMID 39932049, 2025). "Given the essential role of RPAP2 in the growth and survival of HCC cells, the RPAP2 levels must be precisely regulated, likely by a tumor suppressor protein in a negative manner." (PMID 39932049, 2025). "To further investigate whether RPAP2 promotes the in vivo growth of HCC cells, we used a xenograft mouse model and found that lentiviral shRNA‐mediated knockdown of RPAP2 almost completely inhibited the growth of Huh7 and Hep3B cells in vivo, as evidenced by the decreased tumor volume and weight." (PMID 39932049, 2025).
RPAP2 also shares sentences with these, for which no sentence is quoted: emphysema (1 paper); glioma (1); pancreatic (1).